E2F1 (E2F transcription factor 1)
Diseases named in the same sentence as E2F1 in open-access papers (continued):
Sharing a sentence is not in itself a finding about the gene and the disease.
breast carcinoma (continued). "PEPCK‐M promoted the activation of mTORC1 downstream signaling molecules and the E2F1 pathways in ER+ breast cancer." (PMID 35757841, 2023). "Conversely, its expression promoted breast cancer progression by interacting with E2F transcription factor 1 (E2F1), resulting in CDK1 activation in MDA-MB-231 cells." (PMID 37498296, 2023). "Second, we demonstrated that PCK2 regulates the mTORC1 and RB/E2F1 axes and promotes cell proliferation and cell cycle progression in ER+ breast cancer." (PMID 35757841, 2023). "In this study, we showed that PCK2 promotes the proliferation of ER+ breast cancer cells via upregulation of the mTORC1 and RB/E2F1 axes, which affects cell cycle progression." (PMID 35757841, 2023). "PEPCK‐M promotes the proliferation and cell cycle progression of ER+ breast cancer via upregulation of the mTORC1 and E2F1 pathways." (PMID 35757841, 2023). "E2Fs are family of transcription factors involved in cell cycle regulation and altered expression of E2Fs in breast cancer influences survival outcome, as patients with higher expression of E2F1 and cyclin A exhibit very less disease-free survival." (PMID 36774386, 2023). "The role of E2F has been observed in tumour development and metastasis, specifically E2F1 direct metastasis of breast cancer cells by altering cell migration." (PMID 36774386, 2023). "For instance, in breast cancer, E2F1 binds to the SNHG1 promoter and enhances SNHG1 transcription, which in turn promotes hTERT expression by sponging miR-18b-5p." (PMID 37612721, 2023). "It indirectly elevates Cyclin D1 and E2F1 mRNA levels and promotes cell proliferation in breast cancer stem cells." (PMID 36717861, 2023). "A recent study reported that overexpression of miR-302b enhanced the sensitivity of breast cancer cells to cisplatin by regulating the cellular DNA damage response and the expression of E2F1." (PMID 35506202, 2022). "FOXM1 and E2F1 are also upregulated in various types of cancers, such as hepatocellular carcinoma, myeloma, colon cancer, breast cancer, and lung cancer." (PMID 35835838, 2022). "Many reports have found that E2F1 played a central role in cancer development, such as in breast cancer, bladder cancer, and prostate cancer." (PMID 36292703, 2022). "Among the genes in module 1, we found PARP1 and E2F1, recently discovered important genes for endocrine resistance in breast cancer, supporting the validity of our approach." (PMID 35401937, 2022). "In breast carcinoma cells, miR-1258 expression is reduced and miR-1258 can downregulate E2F1 expression." (PMID 36593867, 2022). "Zhou's study shows that NCOA3 can interact with E2F1 to promote the proliferation of hormone-dependent and independent breast cancer cells." (PMID 35898549, 2022). "In breast cancer cells, it was shown that repressing the 17β-estradiol- and heregulin-β1-mediated up-regulation of E2F1 was induced by HES1." (PMID 36012128, 2022). "E2F1 was also discovered to be involved in the production of Nanog in breast cancer and to be up-regulated and engaged in the tumorigenesis of breast cancer." (PMID 35790898, 2022). "For example, KAT2A has been explored to cooperate with E2F1 and be recruited by E2F1 to the promoters of cyclin D1 and cyclin E1, and it is amplified in breast cancer 1 genes." (PMID 36292703, 2022). "The result was consistent with the study in breast cancer, E2F1 bound to the promoter of SEC61G directly and controlled its expression." (PMID 36712687, 2022). "miR-205 is discovered to be a suppressor factor in breast cancer, which can target E2F transcription factor 1, angiomotin, and other genes, and then to reduce cell proliferation, inhibit invasion, and increase apoptosis." (PMID 34306321, 2021). "In order to understand processes underlying breast cancer recurrence in tamoxifen-treated patient cohorts, we considered possible interactions and interplay of ESR1 and E2F1." (PMID 33852600, 2021).
breast carcinoma (continued). "SEC61G overexpression antagonized the effect of E2F1 knockdown in regulating breast cancer cell proliferation, invasion, and apoptosis." (PMID 34039955, 2021). "E2F1, the most investigated member of E2Fs, has been confirmed to have prognostic value in many tumors, such as hepatocellular carcinoma, breast cancer, and pancreatic ductal adenocarcinoma, and spinal osteosarcoma." (PMID 34532281, 2021). "The most recent breast cancer GWAS identified a 2–5 fold increased enrichment of risk SNVs in REs, mostly mapping to the binding sites for breast cancer–associated transcription factors including FOXA1, ESR1, GATA3, E2F1, and TCF7L2." (PMID 34439109, 2021). "A previous study suggested that eugenol suppresses E2F1/survivin and triggers apoptosis in breast cancer cells." (PMID 34502165, 2021). "Taken together, E2F1-mediated regulation promotes the properties of breast cancer and CML CSCs, but has an inhibitory effect on the characteristics of gastric CSCs." (PMID 34476219, 2021). "Future studies are needed to investigate the detailed signaling pathways involved in the E2F1/SEC61G axis regulating breast cancer development." (PMID 34039955, 2021). "In fact, numerous studies have shown that lncRNAs can target E2F1 in cancers, such as lung carcinoma, breast cancer, and BC." (PMID 33816295, 2021). "In invasive bladder cancer and breast cancer, the survival times of patients with low expression of E2F1 and EMT receptor protein signatures were found to be approximately twice as long as those of patients with high expression." (PMID 34476219, 2021). "And targeting blockage of E2F1 anticipated is expected to be a potential therapeutic applicable to breast cancer and CML." (PMID 34476219, 2021). "E2F1 expression has been found to be increased in breast cancer tissue, pointing out the important contribution of this transcriptional factor in breast carcinogenesis." (PMID 33691613, 2021). "CARM1 is recruited at the E2F1 promoter in breast cancer, which upregulates E2F1 expression and alters the expression of downstream cell cycle-related proteins, promoting the proliferation of breast cancer cells." (PMID 34745258, 2021). "This was recapitulated among human HER2+ve breast cancer tumors stratified between low and high E2F1 activity." (PMID 33947907, 2021). "At the same time, several excellent studies have described the abnormally upregulated expression level of E2F1 in lung cancer and breast cancer." (PMID 34564711, 2021). "A study on breast neoplasms and hsa-mir-361 indicated that has-miR-361-3p promotes human breast cancer cell viability by inhibiting the E2F1/P73 signaling pathway." (PMID 34948403, 2021). "Transcriptional factor E2F1, member of E2F family including both transcriptional activators and repressors, is a downstream target of ER pathway resulting overexpressed in breast cancer tissue." (PMID 33691613, 2021). "Taken together, our findings demonstrate that SEC61G promotes breast cancer development and metastasis via modulating glycolysis and is transcriptionally regulated by E2F1." (PMID 34039955, 2021). "E2F1, as an important E2F member, has been reported to be closely related to breast cancer, hepatocellular carcinoma and lung cancer 21-23." (PMID 34659533, 2021). "In breast cancer, the expression of E2F transcription factor 1 was down‐regulated by miR‐885, thus regulating MCF‐7 cell proliferation." (PMID 33710774, 2021). "E2F1 was further reported to drive chemotherapeutic drug resistance in lung and breast cancer cells via activation of ABCG2 expression." (PMID 34476219, 2021). "E2F-1, an important transcriptional factor in the control of cell cycle, proliferation, and carcinogenesis, is often overexpressed in breast cancer tissues compared with normal tissues." (PMID 34563270, 2021). "Although E2F1 has both an oncogenic and oncosuppressive role, it was found that E2F1 overexpression is correlated to poor prognosis in breast cancer." (PMID 32806777, 2020).
breast carcinoma (continued). "This study is designed to clarify that miR-1258 targets E2F1 to regulate the proliferation and cell cycle of breast cancer (BC) cells and consequently suppress the progression of BC." (PMID 32733928, 2020). "Collectively, miR-93 promotes apoptosis of breast cancer cells via repressing E2F1 and CCND1, thereby mediating pAKT activity and apoptosis-related proteins." (PMID 32796817, 2020). "High expression of FGF13 regulated by E2F1 transcription factor was reported to correlate with a shorter cell migration time to metastatic sites in breast cancer." (PMID 33298014, 2020). "Recent findings demonstrated that a novel recombinant adenovirus, targeting E2F-1 and IL-15, has an inhibitive effect on breast cancer proliferation." (PMID 33574894, 2020). "These microRNAs are frequently upregulated in breast cancer and suppress growth control proteins such as E2F1 and PTEN." (PMID 32085745, 2020). "For example, LINC00511 correlates with a poor prognosis in breast cancer, and promotes breast cancer stemness and tumorigenesis via miR-185-3p/E2F1." (PMID 32074085, 2020). "Among downregulated DEGs in Ubc9+/− Lgr5-EGFP+ cells, up to 17% were genes found to be repressed in early gastric cancer, colorectal adenocarcinoma, E2F1-overexpressing hepatocellular carcinoma and a subtype of basal breast cancer." (PMID 32948837, 2020). "Intriguingly, the expression of cdk4, cdk6, e2f1, and rb1 in breast cancer was moderate or low compared to that in all tumors." (PMID 32357912, 2020). "UALCAN cancer database analysis indicated that the expression of cdk4 and e2f1 in breast cancer was significantly higher than that in normal tissues (p < 0.01), while the expression of cdk6 and rb1 was not higher than that in normal tissues." (PMID 32357912, 2020). "To further clarify the underlying mechanism of miR-20b-5p in the regulation of breast cancer cells and stem cells, we chose CCND1 and E2F1 as potential targets based on bioinformatics analysis and preliminary screening by qRT-PCR." (PMID 33008330, 2020). "The effects of miR-1258 and E2F1 on the proliferation and cell cycle of breast cancer cells are determined." (PMID 32733928, 2020). "Overall, we confirmed E2F1 and CCND1 were two direct targets of miR-93, and proved high expression of E2F1 and CCND1 were positively associated with chemoresistance of breast cancer." (PMID 32796817, 2020). "Estrogen via ER induces transcriptional activation of E2F1 which results in the tamoxifen resistance in breast cancer cells." (PMID 32158360, 2020). "For instance, short p42 EBP1 isoform was shown to bind with Rb and represses E2F1 mediated transcription in breast cancer cell lines." (PMID 32283721, 2020). "A recent analysis of highly aneuploidy breast cancers in TCGA found overexpression of three transcriptional regulators, E2F1, MYBL2, and FOXM1." (PMID 32380981, 2020). "ER plays a substantial role in the growth of breast cancer by regulation of cell cycle proteins, such as cyclinD1, E2F1, and c-myc, among others, and tumor cells resistant to CDK4/6i continue to rely on the ER pathway to drive tumor growth." (PMID 31852484, 2019). "Here, we investigated the extent to which TEs contributed binding sites for three breast cancer-associated TFs (C/EBPβ, E2F1 and MYC) in breast cancer." (PMID 31061680, 2019). "Vegfa41, Hbegf42, Hspb143, Flt144, L1cam45, and Plaur46 had significantly lower expression (p < 0.05) in E2F1−/− tumors and have all previously been shown to regulate breast cancer metastasis in vivo." (PMID 31341204, 2019). "Consistent with previous reports in breast cancer cells, we found that E2F1 depletion reduced BRCA1 expression in MDA-MB-231 cells." (PMID 31604914, 2019).
breast carcinoma (continued). "Therefore, CCND1 is highly likely to be the gene that mediates rs614367 breast cancer susceptibility: variants in the enhancer region (either rs614367 or other functional variants) may be hypothesized to drive risk by disrupting E2F1/GATA3/MYC/TCF7L2/ZNF217 binding and affecting CCND1 expression." (PMID 30247654, 2019). "Previous studies have reported that E2F1 is expressed at high levels in most human cancers, including colon cancer and breast cancer and that E2F1 expression in an individual cell facilitates the efficient repair of DSBs and stalled replication forks." (PMID 31534120, 2019). "Despite the different roles of E2F1 in ovarian and breast cancer cells, ZC3H18 depletion reduced BRCA1 levels in both cell lines." (PMID 31604914, 2019). "To further evaluate this possibility, we examined the effect of depleting E2F1 in MDA-MB-231 breast cancer cells." (PMID 31604914, 2019). "We previously showed that MDM2 provides an estrogen-mediated proliferative advantage to breast cancer cells and disrupts acini formation by increasing phosphorylation of Rb and elevating E2F1 protein levels." (PMID 30642351, 2019). "E2Fs are a family of 8 genes and microarrays profiling reported overexpression of some -E2F1/2/3- in breast carcinomas [31 and References therein]." (PMID 31506469, 2019). "Our results showed that PIP5Kα is necessary for breast cancer cell proliferation, as evidenced by the increases in the cell proliferation markers E2F1, CDK1 and CCND1 and the decrease in the tumour suppressor FOXO3." (PMID 29851245, 2018). "E2F1 was also reported to up-regulated and involved in the carcinogenesis of breast cancer and results found it is involved in the expression of Nanog in breast cancer." (PMID 30482236, 2018). "In breast cancer, Hallett and Hassell defined a dual gene classifier to predict breast cancer survival using E2F1 and TUT4 (i.e., KIAA0191; Hallett and Hassell, 2011)." (PMID 30057901, 2018). "So, TFDP3 binding to E2F1 inhibits E2F1-induced apoptosis and increases the tolerance of breast cancer cells to chemotherapeutic agents." (PMID 30235236, 2018). "The characterization of the LINC00511/miR-185-3p/E2F1/Nanog axis provides an important insight for breast cancer stemness and tumorigenesis." (PMID 30482236, 2018). "In conclusion, our data concludes that LINC00511/miR-185-3p/E2F1/Nanog axis facilitates the breast cancer stemness and tumorigenesis, providing a vital insight for them." (PMID 30482236, 2018). "A previous study showed that eugenol suppressed E2F1/survivin and triggered apoptosis in breast cancer cells." (PMID 30518369, 2018). "Results show that E2F1 enhanced Nanog expression at the transcriptional level, providing a potential mechanism by which LINC0051/miR-185-3p/E2F1 axis promotes breast cancer stemness and tumorigenesis." (PMID 30482236, 2018). "We confirmed that 8 genes—MAPK14, CLOCK, NF2, HMGA2, CXCL12, E2F1, NOTCH1, and CD24—are associated with breast cancer." (PMID 30013305, 2018). "In bladder and breast cancer, a network approach distinguished two different receptor protein signatures associated with the E2F1-mediated EMT, E2F1–TGFBR1–FGFR1 in bladder cancer and E2F1–TGFBR2–EGFR in breast cancer." (PMID 29181337, 2017). "This argues for a true relationship between increased MDM2 in breast cancers and the activation of the Rb-E2F1 pathway." (PMID 28615518, 2017). "Here, we use a network approach to identify the tumor type-specific regulatory core and to predict receptor protein signatures associated with E2F1-mediated EMT transitions in two types of highly aggressive solid tumors, bladder, and breast cancer." (PMID 28775339, 2017). "The associations of E2F1, SP1 and estrogen receptor in breast cancer have been described previously." (PMID 27888801, 2017). "In contrast, overexpression of E2F1 and its target genes was found to positively influence E2F1-mediated cell death in ER- breast cancer cells in vitro." (PMID 27888801, 2017).
breast carcinoma (continued). "Overall, model-based treatment recommendations of E2F1-driven tumor diseases such as advanced bladder or breast cancer, have the potential to support cohort-specific treatment of patients to avoid therapy resistance and cope with aggressive cancers." (PMID 28775339, 2017). "Taken together, by combining the predictions from in silico simulations and the in vitro experimental validation, we were able to find molecular signatures that regulate invasive phenotypes in E2F1-driven bladder and breast cancer." (PMID 28775339, 2017). "Long non-coding RNA RAD51 antisense RNA 1 (RAD51-AS1, also known as TODRA) has been shown to be down-regulated by E2F1, a key cell cycle and apoptosis regulator, in breast cancer." (PMID 28667302, 2017). "Our data support that an estrogen-MDM2 axis activates the Rb-E2F1 pathway in at least a subset of breast cancers." (PMID 28615518, 2017). "We have demonstrated for the first time that there is an estrogen-MDM2-Rb-E2F1 axis in some breast cancer cells." (PMID 28615518, 2017). "A similar effect was observed in breast cancer when E2F1, TGFBR2, and EGFR are simultaneously active." (PMID 28775339, 2017). "The data suggested that MALAT1 was involved in cell proliferation through the CDK4/E2F1 signaling pathway in breast cancer." (PMID 26918449, 2016). "Taken together, miR-124 is suppressed by MALAT1, and involved in cell proliferation and the cell cycle via the CDK4/E2F1 signaling pathway in breast cancer." (PMID 26918449, 2016). "Our results revealed a novel breast cancer regulation model that was comprised of the MALAT1-miR-124-CDK4/E2F1 pathway in breast cancer." (PMID 26918449, 2016). "RB1 has been shown to inhibit the E2F1 and E2F2 transcriptional factors; therefore, the allelic deletion of RB1 that was observed in 85% of breast cancer patients in our study is likely to lead to the activation of E2F1 and E2F2." (PMID 26799285, 2016). "Key transcriptional regulators that had been implicated in breast cancer pathogenesis such as RB1, FOXM1 and E2F1 are key targets within our model and the high values of flow differences further highlight their importance in breast cancer." (PMID 26975659, 2016). "In conclusion our study demonstrates that miR-302b overexpression increases sensitivity of breast cancer cell lines to cisplatin by targeting E2F1 and ATM, further compromising the control of cell-cycle progression and DDR mechanisms." (PMID 26623722, 2016). "We have demonstrated that miR-302b sensitizes breast cancer cell lines to cisplatin treatment by targeting directly E2F1 and indirectly ATM, reducing cell growth." (PMID 26623722, 2016). "Our data so far demonstrated that miR-302b overexpression in breast cancer cell lines leads to sensitization to cisplatin treatment, by targeting E2F1 and ATM." (PMID 26623722, 2016). "It had also been reported that E2F1 was deregulated in many types of cancers, such as bladder cancer, breast cancer and lung cancer." (PMID 26655252, 2016). "We now found that E2F7 was responsible for the repression of miR-15a/16 cluster by competing with E2F1 for binding to the promoter of miR-15a/16 host gene DLEU2 in tamoxifen resistant breast cancer cells." (PMID 26397135, 2015). "One of the key proteins suppressed by Rb is E2F1, a transcription factor that binds to and activates H19 promoter, as was shown in breast cancer cells." (PMID 26536864, 2015). "In breast cancer, E2F1 protein regulates ATAD2 gene expression and B-MYB has been reported to have a role in ATAD2 driven cell proliferation." (PMID 26308378, 2015). "Our microarray data also reveal that both E2F-1 and YB-1 were upregulated in Ad5WS1-infected breast cancer cells." (PMID 26515462, 2015).